RACK1 (receptor for activated C kinase 1)
Diseases named in the same sentence as RACK1 in open-access papers (continued):
Sharing a sentence is not in itself a finding about the gene and the disease.
cervical cancer (14 papers, 2016 to 2025). A primary or metastatic malignant neoplasm involving the cervix. "Our results show that RACK1 gene polymorphisms rs1279736 and rs3756585 have a significant effect on cervical cancer." (PMID 40060229, 2025). "In fact, our current study showed the functional importance of two polymorphisms (rs1279736 and rs3756585) in the RACK1 promoter in cervical cancer." (PMID 40060229, 2025). "Since this is the first study in the field of investigating Rack1 polymorphisms, it is hoped that more studies will be conducted in different populations that will lead to the early detection of cervical cancer and its treatment." (PMID 40060229, 2025). "Unveiling the molecular mechanism underlying RACK1 expression or its O-GlcNAcylation will hopefully open new avenues to prevent or overcome nodal metastasis of cervical cancer." (PMID 36658304, 2023). "Furthermore, regulating RACK1 gene expression at the transcriptional level, coupled with the discovery of polymorphisms in the RACK1 promoter associated with increased expression, adds a genetic dimension to its potential role in cervical cancer, warranting comprehensive exploration." (PMID 40060229, 2025). "In cervical cancer, circVPRBP overexpression strongly represses lymph node metastasis by interacting with RACK1 and shielding its S122 O-GlcNAcylation site to accelerate RACK1 degradation." (PMID 40296024, 2025). "The aim of this study is to investigate RACK1 gene polymorphisms, especially rs3756585 and rs1279736, using ARMS PCR and RLFP PCR methods on HPV-induced cervical cancer samples, focusing on squamous cell carcinoma (SCC) compared to the control group." (PMID 40060229, 2025). "Our findings suggest that RACK1 plays a role in the reprogramming of lipid metabolism in cervical cancer, ultimately influencing tumor proliferation." (PMID 39425259, 2025). "Studies have shown that RACK1 is upregulated in cervical cancer tissues compared to normal tissues, with its expression level increasing from cervicitis to cervical intraepithelial neoplasia (CIN) to carcinoma." (PMID 40060229, 2025). "Here, integrated spatially resolved metabolomics and spatial transcriptomics revealed that accumulation of lipids in cervical cancer (CC) samples correlated with overexpression of RACK1, and RACK1 promoted lipid synthesis in CC cells." (PMID 39425259, 2025). "One hundred patients with cervical cancer caused by papillomavirus diagnosed with SCC and 100 healthy subjects were analyzed for RACK1 polymorphism genotypes by H&E staining." (PMID 40060229, 2025). "Next, to detect the role of AKT/mTOR signaling in RACK1‐promoted fatty acid synthesis metabolism in cervical cancer cells, we treated CC cells with SC79 (Akt activator)." (PMID 39425259, 2025). "In our previous research, we identified RACK1 as a potent regulator of metabolism in cervical cancer progression." (PMID 39425259, 2025). "In another study, circVPRBP was shown to bind to RACK1 to inhibit its O‐GlcNAcylation modification at the S122 site, which reduced its stability and inhibited lymph node metastasis in cervical cancer." (PMID 38451046, 2024). "Since RACK1 has the potential to be a theraputic target in cervical cancer LN metastasis, it is pivotal to reach a method accurately shielding O-GlcNAcylation site of RACK1 to destroy its stabilization." (PMID 36658304, 2023). "In this study, we aimed to determine whether the effects of RACK1 on the proliferation and apoptosis of cervical cancer cells depend on fatty acid synthesis mediated by the AKT/mTOR/SREBP1 signaling pathway." (PMID 39425259, 2025). "We previously identified the upregulation of RACK1 in cervical cancer." (PMID 39425259, 2025). "Despite its recognized functions, the exact role of RACK1 in lipid metabolism within cervical cancer remains unclear." (PMID 39425259, 2025). "RACK1 promotes cervical cancer invasion and lymph node metastasis through galectin-1." (PMID 37828084, 2023).
cervical cancer (continued). "Furthermore, rescue experiments supported the fact that circVPRBP abolished the LN metastasis of cervical cancer depending on the RACK1 destabilization." (PMID 36658304, 2023). "Interestingly, the increased receptor for activated C-kinase 1 (RACK1) levels enhanced cervical cancer cell invasion and EMT, and promoted lymphangiogenesis and metastasis in a GAL-1- and β1 integrin-dependent manner." (PMID 37898403, 2023). "It has been reported that RACK1 could participate in the lymphangiogenesis and LN metastasis of cervical cancer in a Galectin-1-dependent manner, suggesting that targeting RACK1 may be a promising strategy." (PMID 36658304, 2023). "Previous literature verified that RACK1 could promote cervical cancer lymphangiogenesis and lymph node metastasis by augmenting Galectin-1-induced downstream FAK, and AKT signaling in cervical cancer cells." (PMID 36658304, 2023). "In addition, tissue microarray in another study revealed abundant levels of RACK1 expression in squamous intraepithelial lesion and cervical cancer." (PMID 32792866, 2020). "Therefore, it was hypothesized that RACK1 may activate AKT/mTOR signaling by interacting with AKT in cervical cancer cells." (PMID 39425259, 2025). "Here, we identified a new concrete regulatory mechanism of decreased RACK1 O-GlcNAcylation by circVPRBP during cervical cancer LN metastasis, suggesting a promising role of circVPRBP on translational applications for the currently limited treatment of cervical cancer nodal metastasis." (PMID 36658304, 2023). "Our findings suggest that RACK1 plays a regulatory role in lipid metabolism by activating the AKT/mTOR/SREBP1 signaling pathway, thereby promoting fatty acid synthesis in cervical cancer cells." (PMID 39425259, 2025). "Four of these genes were also significantly up-regulated in cervical cancer cell lines (SiHa and C33A):EIF3K (p = 0.0092), RACK1 (p = 0.0086), TAPBPL (p = 0.0011) and BTNL8 (p = 0.0012)." (PMID 32025240, 2020). "They identified that oxidative stress-related proteins, such as receptor of activated protein kinase C 1 (RACK1), ras-related nuclear protein (RAN) and peroxiredoxin 1 (PRDX1), were IgG-interacting proteins in HeLa cells (cervical cancer)." (PMID 28536629, 2016). "Our results showed that RACK1 enhances de novo fatty acid synthesis by upregulating the expression of ACC1 and FASN, leading to lipid accumulation and promoting the proliferation of cervical cancer cells." (PMID 39425259, 2025). "Mechanically, to explore whether solamargine regulates the Erk pathway by targeting a specific mRNA, we selected genes reported in recent years to regulate the Erk pathway in cervical cancer, including PBK, RACK1, CXCL3, TRIP4, and SEMA3C, for study." (PMID 36345403, 2022). "RACK1 has been previously found to be upregulated in cancer tissues obtained from 25 cervical cancer patients in comparison with the adjacent non-cancerous tissues." (PMID 32792866, 2020). "In order to investigate whether solamargine regulates the Erk signaling pathway by modulating target mRNAs, we screened out genes that regulate this pathway in cervical cancer including PBK, RACK1, CXCL3, TRIP4, and SEMA3C, which have been reported in the literature in recent years." (PMID 36345403, 2022). "However, our current study found no significant impact of RACK1 on fatty acid oxidation in cervical cancer cells, indicating that RACK1 may promote lipogenesis rather than lipolysis in CC." (PMID 39425259, 2025).
melanoma (13 papers, 2008 to 2025). A malignant, usually aggressive tumor composed of atypical, neoplastic melanocytes. "We chose to study GNB2L1 expression in melanocytes and melanomas in more detail because GNB2L1 encodes RACK1, receptor for activated C kinase, whose mRNA was found to be up-regulated in human carcinomas." (PMID 18442364, 2008). "Concurrently, DHA interacts with the receptor for activated C kinase 1 (RACK1), thus repressing melanoma cell proliferation through the suppression of protein kinase C (PKC) signaling." (PMID 40863616, 2025). "In contrast, other studies have shown that RACK1 promotes cell proliferation in some malignancies, including prostate, breast, lung, cervical, liver, melanoma, and neuroblastoma." (PMID 37848434, 2023). "Both wound-healing and transwell assay were used to observe the effect of RACK1 downregulation on melanoma cell migration." (PMID 31949482, 2020). "RACK1 was significantly high expressed in malignant melanoma tissues, compared with that in normal skin tissues and benign tissues." (PMID 31949482, 2020). "RACK1 was reported as an oncogene in human tumorigenesis, but little is known about its role in melanoma." (PMID 31949482, 2020). "Annexin-V-FITC/PI followed by FCM was performed to evaluate the effect of RACK1 downregulation on melanoma cell apoptosis." (PMID 31949482, 2020). "The present work demonstrates that RACK1 is highly expressed in melanoma tissues and its expression level is well correlated with the clinical progression of melanoma." (PMID 31949482, 2020). "MTT assay was utilized in order to investigate the inhibitory effects of RACK1 downregulation on the growth of melanoma cells." (PMID 31949482, 2020). "To further examine the role of RACK1 in melanoma cells, we designed siRNA (si-RACK1) to downregulate endogenous RACK1 levels in A375 and A875 cells." (PMID 31949482, 2020). "To understand what cellular processes are modulated by RACK1 in melanoma, we investigated the effect of RACK1 downregulation on the functions of A375 and A875 cells." (PMID 31949482, 2020). "Matrigel-based transwell assay was utilized to evaluate the influence of RACK1 depletion on melanoma cell invasion." (PMID 31949482, 2020). "The expression of RACK1 was explored by immunohistochemical staining in total of 107 tissue samples which including 67 cases of malignant melanoma tissues, 23 cases of normal skin tissues and 17 cases of benign tissues." (PMID 31949482, 2020). "This study aimed to investigate the expression of RACK1 in patients with melanoma and to reveal its possible functions in melanoma cells." (PMID 31949482, 2020). "The expression profiles of RACK1 detected in tumor tissues from melanoma patients showed that RACK1 was higher in tumor tissues, and its expression level was well associated with the clinical progression of melanoma (TNM stage, P=0.009)." (PMID 31949482, 2020). "High expression of RACK1 was observed in the cytoplasm of cutaneous and metastatic pig melanoma cells." (PMID 31717496, 2019). "This study pointed at GNB2L1, coding for RACK1, as a potentially interesting gene in melanoma characterization." (PMID 29081790, 2017). "Data provided in this article correspond to the FASTQ files obtained after RNA sequencing of melanoma cells from two mouse models, treated with scramble shRNA or Rack1-targeting shRNA." (PMID 28765829, 2017). "The transcriptome sequencing of melanoma cells from two mouse models differing in the expression level of the scaffold protein Receptor for activated C kinase (RACK1) are presented." (PMID 28765829, 2017). "We extended previous observations on RACK1 expression in melanoma from humans and pigs to melanocytic lesions in horses." (PMID 22747534, 2012). "In the MeWo human melanoma cell line, RACK1 serves as an adaptor protein for PKC-mediated JNK (c-Jun NH2-terminal kinase) activation and increases the survival to UV induced-apoptosis." (PMID 22747534, 2012).
melanoma (continued). "We extend these observations to melanomas in horses which displayed an overexpression of RACK1 when compared to normal cutaneous melanocytes." (PMID 22747534, 2012). "The homogenous distribution pattern of RACK1 signal shared by human, pig, and horse melanomas strongly suggests a function for RACK1 in melanoma progression in mammalian skin." (PMID 22747534, 2012). "We show here that the cellular distribution of RACK1 reflects melanoma progression and aggressiveness: the more homogenous and diffuse the cytoplasmic RACK1 labeling is, the more aggressive the melanoma." (PMID 22747534, 2012). "GNB2L1 encodes the adaptor protein RACK1, recently shown to influence melanoma cell lines tumorigenicity." (PMID 18442364, 2008). "By contrast, RACK1 signal presented two distinct features in melanoma: a dramatic increase of intensity and an homogeneous cytoplasmic distribution over the lesion." (PMID 18442364, 2008). "Altogether, our results on the partial colocalisation of RACK1 and phospho-PKCαβ signal suggest that RACK1 binds more likely to activated PKCβ II than to PKCα in melanoma cells." (PMID 18442364, 2008). "Altogether, screening of human lesions indicates a differential expression of RACK1 in nevi and melanoma." (PMID 18442364, 2008). "These authors further proposed a role for RACK1, specific to melanoma, involving a crosstalk between ERK and JNK signaling." (PMID 18442364, 2008). "RACK1 overexpression was consistently observed in all MITF+ cells from each of the 23 malignant melanoma samples examined." (PMID 18442364, 2008). "In metastases of melanoma to lymph nodes, lung and heart, RACK1 protein was abundant on MITF+ cells." (PMID 18442364, 2008). "Evidence for a role of RACK1 in the pathogenesis of melanoma comes from the recent discovery of the capacity of RACK1 to increase survival of MeWo human melanoma cells following UV induced-apoptosis." (PMID 18442364, 2008). "RACK1 overexpression detected in situ in human melanoma specimens characterized cutaneous and metastatic melanoma raising the possibility that RACK1 can be a potential marker of malignancy in human melanoma." (PMID 18442364, 2008). "By contrast, RACK1 signal was highly increased in the cytoplasm of all melanocytic cells of superficial spreading melanoma, recurrent dermal lesions and metastatic melanoma." (PMID 18442364, 2008). "Taken together, these results demonstrate that RACK1 mRNA and protein are up-regulated in human melanomas as found in pig melanomas, and demonstrate a correlation between the melanoma tumoral status and high levels of RACK1." (PMID 18442364, 2008). "To further investigate the expression of RACK1 in human melanoma, we ascertained its presence in a series of samples." (PMID 18442364, 2008). "Although this study is fairly descriptive, it provides a thorough analysis of RACK1 immunohistochemical detection in human melanoma samples at different stages." (PMID 18442364, 2008). "In most cases, RACK1 has been reported to promote proliferation, radiation and chemotherapy resistance, invasion and metastasis in a variety of cancers, such as lung, liver, breast, esophageal, melanoma, glioma, myeloma and neuroblastoma." (PMID 37848434, 2023). "Taken together, these results suggest that RACK1 may be a poor prognostic factor in human melanoma, and it may be a new therapeutic target for melanoma treatment." (PMID 31949482, 2020). "In addition, RACK1, which was originally found to characterise malignant melanocytic lesions in the MeLiM model and later in human melanomas, has also been found to be effective in distinguishing benign melanocytic tumours from melanomas in horses." (PMID 32652526, 2020). "In conclusion, the present work suggests that RACK1 may be a factor affecting the prognosis of melanoma, and the strategy of RNAi-mediated RACK1 silencing may be an effective method for melanoma treatment." (PMID 31949482, 2020).
melanoma (continued). "More specifically, 62.69% (42/67) of the melanoma tissues showed strong or moderate staining (+++/++) and 37.31% (25/67) showed weak staining (-/+) of RACK-1, while most of control normal skin and benign tissues showed weak staining (-/+), 91.30% (21/23) and 100% (17/17), respectively." (PMID 31949482, 2020). "Moreover, high levels of RACK1 in melanoma tissues were highly correlated with TNM stage (P=0.009), strongly predicted that RACK1 expression was associated with the progression of melanoma." (PMID 31949482, 2020). "Similarly, increased expression of key proteins in melanoma diagnosis and malignancy is elevated in both MeLiM melanomas and human melanomas, such as S100, RACK1, and tenascin C." (PMID 32652526, 2020). "In the present study, RACK1 knockdown resulted in inhibition of cell proliferation and promotion of cell apoptosis of A375 and A875 cells; in vitro study also showed that the migration and invasion of melanoma cells were inhibited." (PMID 31949482, 2020). "Moreover, depletion of endogenous RACK1 lead to decreased proliferation, migration and increased apoptosis of melanoma cells." (PMID 31949482, 2020). "Moreover, the receptor for activated C kinase 1 (RACK1) protein was found as a useful marker to discriminate melanoma cells from healthy skin and melanocytic lesions." (PMID 31717496, 2019). "Because of similar findings in human cutaneous melanomas and melanoma metastases, RACK1 expression could serve as a potential marker of malignancy of human melanoma." (PMID 31717496, 2019). "RACK1 may allow cross-talks between several pathways involved in melanoma development through the orchestration of protein-protein interactions." (PMID 22747534, 2012). "RACK1 emerges as an important marker of malignancy which may contribute to progress in the diagnosis of melanomas in both human and veterinary medicine." (PMID 22747534, 2012). "We now confirm the usefulness of RACK1 labeling as a diagnosis marker for melanoma." (PMID 22747534, 2012). "We tested whether the cytoplasmic distribution of RACK1 staining could be of help in classifying melanoma lesions." (PMID 22747534, 2012). "Indeed RACK1 is strongly detected in melanoma cells of primary tumors and metastases developed in MeLiM minipigs as well as in human patients." (PMID 22747534, 2012). "Finally, we found that RACK1 labeling can be used in horses to distinguish benign melanocytic tumors from melanomas." (PMID 22747534, 2012). "On the other hand, a homogeneous staining for RACK1 only appeared on melanomas." (PMID 22747534, 2012). "In this study, we tested the value of RACK1 detection in the diagnosis of horse melanoma." (PMID 22747534, 2012). "Particularly, there is evidence for a role of RACK1 in the pathogenesis of melanoma." (PMID 22747534, 2012). "Two samples identified as melanomas also stained heterogeneously for RACK1." (PMID 22747534, 2012). "It is noteworthy that melanoma cell lines express even more RACK1 than cultured melanocytes." (PMID 18442364, 2008). "Indeed, we found that the adaptor protein RACK1 in pig melanoma is overexpressed as in human melanoma." (PMID 18442364, 2008). "Thus, in MeLiM, RACK1 overexpression in tumoral tissues was observed in the cytoplasm of melanoma cells at different stages of progression, from cutaneous melanoma to melanoma metastases, with an additional nuclear localisation in MMC." (PMID 18442364, 2008). "Moreover, RACK1 expression was strongly related with the TNM stage of melanoma (P=0.009)." (PMID 31949482, 2020). "Thus, our results indicate that RACK1 contributes to the tumorigenesis and progression of melanoma." (PMID 31949482, 2020). "Thus, cytoplasmic RACK1 labeling may be helpful in distinguishing melanoma from benign melanocytic skin tumors." (PMID 22747534, 2012). "Finally, we checked whether activated protein kinase C (PKC) was a partner of RACK1 in melanoma cells." (PMID 18442364, 2008).